HPSE (heparanase)
Diseases named in the same sentence as HPSE in open-access papers (continued):
Sharing a sentence is not in itself a finding about the gene and the disease.
tumor (continued). "HPSE and USF1 staining were predominantly in the nuclei, and the positive signal was brown-yellow granules in tumor cell nuclei." (PMID 25149140, 2014). "Serum heparanase levels have also been reported to be higher in patients with large tumors (>5 cm), advanced pTNM stage (III and IV), tumor capsule absence, and portal vein invasion." (PMID 25105093, 2014). "Both heparanase and Sulf2 are capable of increasing expression of HSPG targeted to the cell surface and, consequently, increasing pro-tumor signaling by HS-binding growth factors." (PMID 25105093, 2014). "In this study, we found the relative expression levels of HPSE and USF were significantly increased in the HCC cell lines and HCC tumor tissues compared with the normal liver cell line or corresponding NTST." (PMID 25149140, 2014). "LMWH competes with heparanase for the HS acceptor, reducing the degradation of HS and thereby maintaining an intact ECM and inhibiting infiltration and metastasis by the tumor." (PMID 25187827, 2014). "This suggests that heparanase and T5 affect different aspects of RCC tumor progression which complement each other." (PMID 23251556, 2012). "This is due exclusively to the absence of the module's input enzyme, heparanase (K07964-5), a typically eukaryotic gene family implicated in tumor metastasis; the healthy commensal microbiota may thus lack this activity in order to avoid undesirable inflammatory and immune response in the gut." (PMID 22719234, 2012). "PG500 series compounds are believed to interfere with two important processes in tumor development, namely angiogenesis via inhibition of VEGF, FGF-1, and FGF-2, and metastasis via inhibition of heparanase activity." (PMID 23908791, 2011). "Among these mediators, stand out pro-angiogenic factors, such as heparanase and vascular endothelial growth factor (VEGF) and tryptase and chymases that provide tumor growth." (PMID 20569458, 2010). "In conclusion, our data demonstrate for the first time HPSE expression and activity in RMS and highlight its involvement in tumor cell invasion as revealed by shRNA silencing." (PMID 19715595, 2009). "In conclusion, we detected for the first time HPSE expression and activity in RMS and showed its implication in tumor cell invasiveness in vitro." (PMID 19715595, 2009). "Thus, heparanase may affect several key signaling components essential for tumor progression." (PMID 18647407, 2008). "In this study, we examined the expression of heparanase protein and mRNA in human PDA cell lines and tumours." (PMID 11953884, 2002). "Secretion of tissue factor and proinflammatory cytokines by tumor cells and the TME, overexpression of heparanase and podoplanin, impaired fibrynolysis and increased neutrophil extracellular trap formation lead to platelet hyperactivation resulting in hypercoagulability in PC." (PMID 41899496, 2026). "Given that heparanase and HMGB1 can both modulate the tumor microenvironment and facilitate metastasis, targeting these parallel pathways may offer synergistic benefits in aggressive cancers such as TNBC." (PMID 40277915, 2025). "Immunohistochemical analyses of patient samples revealed that invasive tumor regions exhibited strong HPSE positivity, whereas adjacent healthy tissues displayed no detectable signal." (PMID 41301515, 2025). "In mammals, heparanase (HPSE), the sole endo-β-D-glucuronidase, is vital for breaking down extracellular elements and secreting angiogenic and growth-enhancing substances, thus facilitating tumor development, invasion, metastasis, and angiogenesis." (PMID 39201782, 2024). "Heparanase is an endoglucuronidase that cleaves heparan sulfate (HS), thereby altering the structure and function of heparan sulfate proteoglycans (HSPG) and contributing to tumor-mediated remodeling of the cell surface and extracellular matrix (ECM)." (PMID 38334603, 2024).
tumor (continued). "However, the expression of phospho-AKT and heparanase was lower in AS10-treated 4T1 and CT26 tumor-bearing mice, as demonstrated by Western blotting." (PMID 39247596, 2024). "Applying the Mia PaCa-2 tumor model, we investigated whether compound XII also affected the levels of heparanase protein in PDAC tumors." (PMID 38334603, 2024). "On the other hand, heparanase displays non-enzymatic properties in numerous studies, influencing the tumor microenvironment." (PMID 39247596, 2024). "In addition, heparanase upregulates the expression of multiple genes (i.e., VEGF, HGF, RANKL, MMP-9, IL-2, and IFN-γ) that promote aggressive tumor progression and inflammation." (PMID 38334603, 2024). "Heparin and its mimetics show promise in selectively inhibiting heparanase expression while also targeting essential mediators such as fibroblast growth factors (FGFs) and the vascular endothelial growth factor (VEGF) involved in tumor angiogenesis." (PMID 39459002, 2024). "Herein, we demonstrated that AS101 downregulates heparanase through the AKT signaling pathway in murine breast cancer and colon carcinoma models (widely used for their highly metastatic properties), and it exhibits significant inhibition of tumor metastasis." (PMID 39247596, 2024). "This should be taken into account when systemically treating patients with heparanase expressed CAR cells, since the potential adverse effect on ECM degradation might also lead to tumor dissemination." (PMID 39415291, 2024). "In contrast, our present study suggested no distinct role for HPSE in mammary gland branching morphogenesis of mammary glands examined at the ethical tumour volume end point." (PMID 37297024, 2023). "Following the generation of the MMTV-PyMTxHPSE−/− mice described herein, it was necessary to also demonstrate the lack of HPSE expression localised specifically to regions of tumour lesions in the mammary glands of female MMTV-PyMTxHPSE−/− mice." (PMID 37297024, 2023). "Heparanase levels presented differences between non-tumor adjacent tissue and tumor tissue, differences between stages in the same tissue, and an interactive effect between tissue and stage." (PMID 36139645, 2022). "By bioinformatics analysis, heparanase (HPSE) was identified as a prognostic biomarker in ESCC independent of tumor purity and hypoxia, a finding that was verified by IHC." (PMID 35840985, 2022). "In addition to heparanase and VEGF-B results previously explained in non-tumor adjacent tissue, the IκB ratio presented the higher levels at stage II in non-tumor adjacent tissue." (PMID 36139645, 2022). "MMP9 results showed a similar pattern to non-metastatic stages (I, II, and III) in tumor tissue heparanase levels, as MMP9 presented a huge increase in tumor tissue compared to non-tumor adjacent tissue, especially in stage II." (PMID 36139645, 2022). "HPSE also exhibits a variety of non-enzymatic functions, such as regulating gene expression, promoting cell adhesion, and tumor-promoting procoagulant activity." (PMID 36340029, 2022). "Heparanase-2 (HPSE2), a secreted protein that shares 40% homology to HPSE, interestingly does not exhibit glycosidase activity but can block HPSE activity and act as a tumor suppressor." (PMID 35294848, 2022). "Although HPSE has been proposed as a prognostic marker in ESCC, it is unclear whether and how it plays a role in tumor metastasis." (PMID 35840985, 2022). "However, both the MMP-9 and HPSE, whose expression is upregulated in many primary human tumors, including CRC, and plays a primary role in tumor development and metastasis, were moderately expressed also in concentrated Matrigel samples." (PMID 36551219, 2022). "Tumor tissue showed an increase in heparanase levels compared to non-tumor adjacent tissue, in all four stages." (PMID 36139645, 2022).
tumor (continued). "In addition, overexpression of heparanase (HPSE), an enzyme that can degrade major components of the extracellular matrix, on CAR T cells effectively promotes tumor T-cell infiltration and antitumor activity." (PMID 35874717, 2022). "Additionally, heparanase regulates the levels of phosphorylated Focal-adhesion kinase (FAK), SRC, and paxillin, adhesion molecules required for tumor cell cluster formation, the process that facilitates cancer metastasis." (PMID 34681753, 2021). "The subsequent uptake of soluble heparanase by tumor cells initiated ERK and Akt signaling pathways, stimulated the expression of vascular endothelial growth factor (VEGF), HGF, and MMP-9, and was correlated with an aggressive tumor phenotype." (PMID 33800172, 2021). "The results revealed that BC-derived heparan sulfate (HS) could be carried by exosome particles, leading to upregulation of ﻿heparanase (HPSE) and HPSE2 expression of lymphocytes, which was highly relevant for cellular migration and tumor metastasis." (PMID 34039961, 2021). "Furthermore, Salmonella decreased heparanase expression in B16F10 and 4T1 tumor cells by suppressing the phosphorylation of AKT." (PMID 34220326, 2021). "Regardless of molecular type, tumour diameter, lymph node involvement, staging, and grade of tumour, the concentration of heparanase also significantly decreased after adjuvant treatment." (PMID 34070058, 2021). "Accordingly, while macrophages were noted to populate the entire tumor mass in control mice, they appeared to accumulate at the tumor periphery in heparanase-KO mice or upon treatment with pixatimod (PG545) or defibrotide, suggesting that heparanase is required for macrophages to penetrate tumors." (PMID 35069219, 2021). "Heparanase can be used to regulate Sdc-1 levels in the nucleus; however, removal of HS from the nucleus by nuclear heparanase promotes an aggressive tumourigenic phenotype by enhancing HAT activity, which elevates the expression of tumour-promoting genes." (PMID 33922532, 2021). "Indeed, HPSE inhibition by PG545 has been shown to downregulate autophagy by regulating LC3 expression, a well-known marker of autophagy, in tumour xenograft models of human pharyngeal carcinoma." (PMID 34677445, 2021). "Even though no direct evidence linking HPSE expression and T cells in a physiological anti-tumour setting has yet been reported, such a relationship can be strongly suggested based on these observations." (PMID 33256730, 2020). "These tumor chemoexosomes can remodel extracellular matrix by degrading ECM heparan sulfate and/or by transferring their heparanase cargo to cells where HS degradation will induce signal activation, resulting in enhanced secretion of an important myeloma growth factor, TNF-α, by macrophages." (PMID 31963505, 2020). "HPSE also exhibits a variety of non-enzymatic functions such as regulating gene expression, promoting cell adhesion and tumour-promoting pro-coagulant activity." (PMID 33256730, 2020). "On one hand, heparanase is overexpressed in many tumors and the active form of the enzyme is released extracellularly, therefore, explaining the rational of employing HPSE inhibitors to block tumor progression." (PMID 31963505, 2020). "As the tumor evolves, the stroma undergoes tissue remodeling under the action of enzymes able to modify the glycosidic chains of the ECM, i.e., glycosyltransferases, sulfotransferases, sulfatases, and heparanase." (PMID 31963505, 2020). "Heparanase (HPSE), the only recognized mammalian endo-β-D-glucuronidase, is responsible for the cleavage of heparan sulfate (HS) chains of heparan sulfate proteoglycans (HSPGs) in the ECM as well as on the tumor cell surface." (PMID 31001480, 2019). "In conclusion, our data demonstrate that HPSE knockdown attenuated tumor growth and liver metastasis in CRC, implying that HPSE might serve as a potential therapeutic target in the treatment of CRC." (PMID 31001480, 2019).
tumor (continued). "Additionally, heparanase mediates upregulation of MMP-9, expressed from tumor cells, to indirectly stimulate invasion." (PMID 32010611, 2019). "Knockdown of HPSE is accompanied by downregulation of MMP1, MMP7, MMP10, and MMP13, all of which are directly involved in the degradation of extracellular matrix and facilitate tumor cell invasion." (PMID 31001480, 2019). "It is apparent from the analysis described here that heparanase is not a straight-forward anti-cancer drug target despite the wealth of evidence to indicate it contributes to tumor growth, tumor cell migration, metastasis formation, and chemoresistance." (PMID 31850210, 2019). "The notion that heparanase, through its enzymatic activity, releases sequestered pro-angiogenic growth factors like VEGF, and so facilitates VEGF receptor interactions and angiogenesis in tumor models has been demonstrated." (PMID 31850210, 2019). "It is perhaps predominantly through this mechanism of leukocyte activation that this inhibitor exerts its anti-cancer activity, rather than direct tumor cell-heparanase inhibition." (PMID 31110966, 2019). "Regardless of the source of heparanase, its inhibition with the heparanase neutralizing antibody Ab 1453 in these tumors was sufficient to reduce tumor growth." (PMID 31110966, 2019). "In the mid-late 1980s, we and others demonstrated that the ability of heparin to inhibit metastasis was consistent with its ability to inhibit heparanase released by tumor cells, and this activity was independent of heparin's anticoagulant activity." (PMID 31850210, 2019). "Active heparanase, by unknown mechanisms, increases both VEGF-C transcription and tumor invasiveness." (PMID 29527513, 2018). "Of note, anti-myeloma chemotherapy stimulates the elevated secretion of EVs containing high levels of heparanase on their surface, which degrade ECM and can be transferred to both tumor and host cells, altering their behavior in a way that enhances tumor survival and progression." (PMID 30322133, 2018). "Paradoxically, however, most studies examined heparanase levels in the primary tumor and not in the resulting metastases that are the prime target of heparanase inhibitors." (PMID 29464068, 2018). "Endogenous T-cells express heparanase, an ECM-degrading enzyme, which enhances their ability to penetrate this stroma; however, heparanase expression is often lost during in vitro culture, preventing CART from entering tumor sites." (PMID 30386740, 2018). "As exemplified in patients 5 (p5), 57 and 25, the primary tumor is stained negative for heparanase while the metastasis lesion is stained strongly." (PMID 29464068, 2018). "Heparanase, the sole endoglycosidase in mammals is considered as a bad prognostic marker in different malignancies, based on its capacity to cleave HSPGs, to remodel ECM and to turn tumor cells into chemoresistance." (PMID 28978053, 2017). "It is therefore not surprising that a HS degrading enzyme, heparanase, is critically involved in pathological processes, including tumor growth, metastasis, angiogenesis, thrombosis, fibrosis, inflammation, autoimmunity and kidney dysfunction." (PMID 28388547, 2017). "Immunohistostaining of the tumor sections with anti-heparanase antibody revealed strong signals in the non-treated tumor sections; while the heparanase positive signals were significantly reduced in the tumor sections treated with GYII and fucoidan." (PMID 28505136, 2017). "The current saccharide-based compounds are not specific for heparanase leaving open the question as to how much of their anti-tumor effect is due specifically to blocking heparanase activity." (PMID 28359266, 2017). "HPSE expression is elevated in highly metastatic tumor cells, and transfection of HPSE into non-metastatic tumor cells increased their metastatic ability (vs. control), while HPSE knockout decreased invasive and metastatic ability." (PMID 28388549, 2017).
tumor (continued). "Moreover, heparanase, an endo-β-glucuronidase capable of cleaving heparan sulfate (HS), participates in the degradation of the ECM and hence prompts tumor progression and metastasis." (PMID 28505136, 2017). "We have demonstrated that MM tumors formed from CAG cells expressing high levels of heparanase grow and progress to bone much more readily than CAG tumors expressing low levels of heparanase and that the HPSE inhibitor SST0001 inhibits tumor growth in MM animal models." (PMID 26849235, 2016). "Heparanase enzymatic activity was practically identical in control (Vo #12) and Hpa2 (#B4) cells, suggesting that the decrease in tumor growth is not due to inhibition of heparanase activity by Hpa2." (PMID 26968815, 2016). "Heparanase is an endoglycosidase that cleaves heparan sulfate proteoglycans (HSPG) to alter the structure of the extracellular matrix (ECM), and also plays an important role in tumor metastasis." (PMID 27563824, 2016). "Heparanase also interacts with tissue factor pathway inhibitor (TFPI) on the cell surface, leading to dissociation of TFPI from the cell membrane of endothelial and tumor cells, resulting in decreased anticoagulant capacity at the cell surface." (PMID 27322195, 2016). "Although a number of studies in many tumour types have supported these conclusions, a unifying mechanistic explanation of precisely how heparanase promotes angiogenesis and metastasis was lacking until recently." (PMID 27408707, 2016). "Likewise, studies concerning effects of therapy on tumor microenvironment and on the CD138/heparanase axis are greatly required in this context, in order to assess beneficial effects of administered drugs." (PMID 26025441, 2015). "In addition, VEGF expression is significantly upregulated in cells expressing high levels of heparanase, leading to decreased nuclear SDC-1 and an aggressive tumor phenotype." (PMID 24551591, 2014). "Yet, the molecular pathways responsible for induction of heparanase expression in malignant tumours, versus lack of expression in normal tissues of the same origin (including HNSCC) 23,28,38 remain poorly understood." (PMID 24286246, 2014). "It is therefore not possible to document the heparanase level during the developmental stages of the tumor." (PMID 24887057, 2014). "Heparanase upregulation in cancer cells from myeloma, lymphoblastoid and breast cancer reflects in augmentation of exosome secretion with an enhanced content of syndecan-1, VEGF and HGF whose roles are closely related to tumor aggressiveness." (PMID 25295847, 2014). "In addition, both heparanase and SDC-1 are retained as cargo within exosomes and subsequently influence not only the behavior of the tumor microenvironment within the tumor niche and distant sites, but also the growth of the metastasizing cells." (PMID 24551591, 2014). "It has been postulated that heparanase and HSPGs act synergistically within the tumor microenvironment to enhance tumor growth and the enzymatic versus non-enzymatic roles of heparanase in cancer have been discussed elsewhere." (PMID 25105093, 2014). "In contrast, in seven of 10 p16-negative tumours examined, no heparanase overexpression was detected." (PMID 24286246, 2014). "Heparanase, Sulf1, and Sulf2 have been shown, by virtue of their enzymatic modification of the ECM, to affect the signaling of a number of proteins that are important drivers of tumor growth or progression." (PMID 25105093, 2014). "High level of heparanase implies low levels of nuclear syndecan-1 and increased histon acetyl transferase (HAT) activity leading to enhanced transcription of VEGF and MMP-9, both known to drive an aggressive tumor phenotype." (PMID 24392351, 2013). "The heparanase tumor antigen is not able to elicit an immune response; however, conjugation of heparanase to Lex was able to stimulate IFN-gamma cytokine secretion by T cells, CTL responses and delay the growth of established tumors in mice." (PMID 24228179, 2013).